IL6 (interleukin 6)
Diseases named in the same sentence as IL6 in open-access papers (continued):
Sharing a sentence is not in itself a finding about the gene and the disease.
osteoporosis (continued). "Omega-3 PUFAs induce anti-inflammatory effect on bones, leading to a decrease in pro-inflammatory cytokines (interleukin-1, interleukin-6 and tumour necrosis factor-alpha) that play a critical role in bone renewal and are involved in osteoporosis." (PMID 23750339, 2013). "Several cytokines such as IL-1, IL-6, RANKL, OPG, and M-CSF were implicated in the pathogenesis of osteoporosis." (PMID 22162676, 2012). "Most of all, IL-6 expression was significantly elevated in male TH mice, suggesting an important role for IL-6 in osteoporosis development in male TH mice." (PMID 21464945, 2011). "Inflammatory cytokines, including IL-1β, IL-6 and TNF-α, are also responsible for the characteristic loss of bone density in osteoporosis through their effect on osteoclast activity." (PMID 22176920, 2011). "Interleukin 6 (IL6) is an important mediator of fever and the gene has been associated with osteoporosis and Kaposi's sarcoma." (PMID 20011102, 2009). "Interleukin-6 mediated inflammation contributes to bone resorption and osteoporosis by stimulating osteoclastogenesis and osteoclast activity." (PMID 17374166, 2007). "IL-6 has a complex regulatory mechanism in the development of sarcopenia-osteoporosis." (PMID 41495343, 2026). "Interrupting the vicious cycle between Periostin and IL-6 or TGFβ could be a potential target for new therapeutics in osteoporosis." (PMID 39940700, 2025). "This would be dysregulated in osteoporosis with increased IL-6 and Periostin expression and could also be used therapeutically to slow inflammation and bone loss." (PMID 39940700, 2025). "IL-6 from MSCs has been shown to induce differentiation and activation of osteoclasts via the RANK ligand (RANKL), which is associated with bone resorption and osteoporosis." (PMID 40699630, 2025). "Osteoporosis has been linked to changes in gut microbiota, particularly a reduction in Lactobacillus species and an increase in pro-inflammatory cytokines such as TNF-α, IL-6, and IL-14 in the serum." (PMID 40422878, 2025). "The association between DANCR, IL-6, and TNF-α in osteoporosis therapies remains under examination." (PMID 41158629, 2025). "Interestingly, IMB-R38 treatment significantly decreased mRNA levels of Mmp9, Mmp13, Mmp2, and Il-6, which play a vital role in both osteoporosis and inflammation." (PMID 41465573, 2025). "Understanding the biological effects of IL-6 may help to discover novel targets in the treatment of osteoporosis." (PMID 39200293, 2024). "Studies have indicated that acupuncture at the ST36 acupoint reduced serum IL-1β expression in ovariectomized rats; generally, acupuncture can mitigate bone destruction and slow the progression of osteoporosis by downregulating inflammatory factors such as tumor necrosis factor-α and interleukin-6." (PMID 39588119, 2024). "Osteoporosis with severe alterations in cortical and trabecular bone microarchitecture, accompanied by a decrease in the number of osteoblasts and an increase in osteoclasts, is observed in IL-6 transgenic mice." (PMID 38473934, 2024). "Dex causes osteoporosis by increasing oxidative stress, decreasing antioxidant markers, reducing bone growth markers (OPG and OCN), and increasing bone turnover and resorption markers (NFATc1, RANKL, ACP, ALP, IL-6, and TNF-α)." (PMID 38247490, 2024). "IL-10 knockout mice develop osteoporosis and have significantly increased expression of the inflammatory factors IL-6 and TNF in bone, and treatment with E2 ameliorates this process, suggesting that the development of inflammation in bone is closely linked to estrogen deficiency." (PMID 38895114, 2024). "Further evidence demonstrates that blood mononuclear cells with upregulated DANCR expression could lead to osteoporosis, thereby increasing the secretion of IL-6 and TNF-α as well as bone resorbing activity." (PMID 38589566, 2024). "Many researchers study the influence of IL-6 in osteoporosis." (PMID 39200293, 2024).
osteoporosis (continued). "Thus, exploring the relationship between IL-6, other inflammatory factors, and estrogen will deepen the understanding of the pathogenesis of osteoporosis." (PMID 37035758, 2023). "This study compared the baseline characteristics of postmenopausal women in the normal and osteoporosis groups and found that the two groups had statistically significant differences in age; years since menopause; circulating IL-6, PTH, and IGFBP-3; LS BMD; and FN BMD." (PMID 37035758, 2023). "IL-6 can also promote osteoclastic activity and bone loss by activating the osteoprotegerin/receptor activator of nuclear factor kappa B ligand/receptor activator of the nuclear factor kappa B (OPG/RANKL/RANK) system, leading to osteoporosis." (PMID 37035758, 2023). "Furthermore, vitamin E has been reported to be anti-inflammatory in preventing osteoporosis, regulating cytokines, such as IL-1, IL-6, RANKL, OPG, and M-CSF, critical determinants of osteoclast differentiation, and bone resorptive activity." (PMID 37107290, 2023). "The findings of this work are important because they also highlight that the beneficial effects of stimulation with PEMF are comparable to those of knockout mice for the TNF-α or IL6 genes, suggesting a role of these two mediators in post-menopausal osteoporosis." (PMID 35336776, 2022). "IL6, CXCR4, IGF1, and PLOD2 played crucial roles in weightlessness osteoporosis, which provided a theoretical basis for the pathogenic mechanism and treatment of weightlessness osteoporosis." (PMID 35479581, 2022). "Furthermore, it has been postulated that interleukin-6 (IL-6) and some other cytokines play a significant role in the pathogenesis of osteoporosis." (PMID 35204134, 2022). "Meanwhile, many relevant biomarkers have shown the correlation between osteoporosis and already been used to auxiliary diagnose OP and assess bone metabolism, such as leptin, Interleukin-6 (IL-6), insulin-like growth factor 1 (IGF-1), and vascular endothelial growth factor (VEGF)." (PMID 35993023, 2022). "IL-6 is responsible for osteoporosis and joint destruction in RA patients." (PMID 35422870, 2022). "The treatments could beneficially improve osteoporosis indicators; enhance calcium, phosphorus, osteocalcin, and calcitonin levels; reduce hydrogen peroxide, and IL-6, and antioxidant biomarkers." (PMID 36235920, 2022). "The literature indicated that oleuropein in olive oil could prevent osteoporosis by inhibiting the expression of IL-6 in osteoblasts and decreasing the expression of RANKL in osteoblasts." (PMID 36060661, 2022). "Even more, Sylvester and coworkers highlighted that IL-6 is the sole cytokine with repeatedly increased serum values in CD patients, being constantly present in the circulation of individuals with coexisting osteoporosis." (PMID 35334519, 2022). "Biological DMARDs targeting TNF and IL-6 inhibit synovitis and bone and cartilage destruction, but do not influence the risk of osteoporosis." (PMID 33802804, 2021). "What is more, serum Ca and Mg levels negatively correlated with the level of IL-6 in a group of obese women, which may contribute to osteoporosis in the menopause, when estrogen levels are reduced." (PMID 34890370, 2021). "Apigenin treatment of TNF-a-induced MC3T3-E1 osteoblasts, reduced its production of IL-6 and NO involved in bone resorption, suggesting apigenin’s intervention in treating bone disorders such as osteoporosis characterised by excessive production of inflammatory cytokines." (PMID 34887836, 2021). "In addition, many studies reported that proinflammatory cytokines and their related genes such as galectin, NLRP3, and IL-6 have a significant pivotal role in the destruction of bones and severity of osteoporosis." (PMID 34938374, 2021). "The plausible cause for this could be that in osteoporosis, the proinflammatory cytokines such as serum levels of IL-6, leptin, IL-1, and resistin increases and might be the main contributing factor in the pathogenesis of osteoporosis." (PMID 33519717, 2020).
osteoporosis (continued). "Moreover, we noted significantly reduced expression of IL-6 which is common cytokine characteristic for osteoporosis." (PMID 32933533, 2020). "The level of 14-3-3η and IL-6 presented with the highest value in the osteoporosis group, but the lowest value in the normal group, and there were significant differences in the level of 14-3-3η and IL-6 among the groups (p<0.05), and there was positive correlation between 14-3-3η and IL-6 (p<0.05)." (PMID 32704255, 2020). "On the other hand, there was no change in the expression of IL-6, IL-1β or IL-23a, which are cytokines associated with osteoporosis." (PMID 32443893, 2020). "Although TNF, IL-1, and IL-6 play an important role in the activation and differentiation of osteoclasts, current studies have not fully confirmed the role of proinflammation in the pathogenesis of osteoporosis." (PMID 32509864, 2020). "In vitro studies showed that genistein or daidzein could decrease bone resorption and promote bone formation by regulating the expression of OPG and RANKL as well as suppressing TNF-α and IL-6, so as to prevent osteoporosis." (PMID 33447176, 2020). "As is well known, estrogen plays a protective role in the development of osteoporosis, indirectly inhibiting osteoclast activity through the down-regulation of pro-inflammatory cytokines (IL-1, IL-6, TNF-α, M-CSF) and the up-regulation of TGF-ß, an inhibitor of bone resorption." (PMID 31540048, 2019). "IL-18, IL-6 and hs-CRP are risk factors for trabecular bone destruction in osteoporosis patients." (PMID 31258577, 2019). "Cytokines other than RANKL and OPG, such as interleukin (IL)-1α, IL-6 and tumor necrosis factor-α, that are largely recognised as important effectors in the pathogenesis of several forms of osteoporosis, could have a role in TM-related osteoporosis." (PMID 29991466, 2019). "IL-6, TNFα and TGFβ might be involved in osteoporosis through the regulation of osteoblastogenesis and osteoclastogenesis." (PMID 25364723, 2014). "IL-6 has been demonstrated to directly increase the viability of osteoclasts, inhibit their apoptosis and increase the length of their life cycle, resulting in osteoporosis." (PMID 24926367, 2014). "IL-6 was also reported to be produced by osteoblasts and can induce RANKL mRNA expression, promote the differentiation of osteoclasts from its precursor and play an important role in the pathogenesis of osteoporosis due to estrogen deficiency." (PMID 23437352, 2013). "This suggestion does not exclude other possible links not related to vitamin D between MS and osteoporosis, including shared genetic risk factors, and genetic variation in the interleukin-6 gene is one example that has been associated with both diseases." (PMID 23029191, 2012). "Several animal studies have shown that vitamin E in the forms of palm-derived tocotrienol and α-tocopherol may prevent osteoporosis in rat models by suppressing IL-1 and IL-6." (PMID 22162676, 2012). "The role of IL-6 as a stimulator of bone resorption in post-menopausal osteoporosis is well-known." (PMID 21696618, 2011). "In the presence of soluble IL-6 receptor, IL-6 has been shown to activate osteoclasts to induce bone resorption in vitro, suggesting that IL-6 may be involved in osteoporosis." (PMID 20691044, 2010). "Furthermore, in terms of bone metabolism, IL-6 induces osteoclast differentiation in the presence of soluble IL-6 receptor, thereby contributing to joint destruction and osteoporosis." (PMID 19019215, 2008). "In addition, both the calcium-sensing receptor (CASR) and the interleukin 6 (IL-6) are important candidate genes for osteoporosis as well as in bone and mineral metabolism." (PMID 18036257, 2007). "Given that IL-6 blockade reduces bone resorption in inflammatory diseases, asiatic acid may represent a natural, multi-target adjunct candidate for inflammation-driven osteoporosis, particularly in postmenopausal or chronic inflammatory settings." (PMID 41562931, 2026).
osteoporosis (continued). "Therefore, IL-6 appears to be the primary inflammatory factor influencing osteoporosis." (PMID 40421249, 2025). "Furthermore, combined treatment with dexamethasone plus estrogen in these same mice (ovariectomized DBA/1) reduced B-cell frequency, autoantibody concentration, and inflammation incidence (IL6), reducing disease manifestations, cartilage destruction, and osteoporosis." (PMID 40283539, 2025). "Similarly, results from the Framingham Osteoporosis Study, showing a lack of associations between IL-6 and aBMD at the hip and spine, are also in agreement with our findings." (PMID 40329072, 2025). "In addition, data reveals that the hBMSCs derived from aging patients with osteoporosis highly expressed IL-6, which may play the role of immunomodulation and alter the immune circumstance of the bone cavity microenvironment." (PMID 38791313, 2024). "Furthermore, it has been observed that Th2 dominance is related with senile osteoporosis, implying that Th2-type cytokines such as IL-10, IL-6, IL-5, and IL-4 levels rose while Th1-type cytokines such as IL-2,IFN-γ and TNF-α reduced in patients suffering from senile osteoporosis." (PMID 38461235, 2024). "However, we believe that since osteoporosis is a chronic systemic disease associated with proinflammatory cytokines, such as IL-6 and tumor necrosis factor (TNF)-alpha, studies with long-term follow-up periods are needed to determine the link between LTL and osteoporosis." (PMID 39074257, 2024). "Marrow fat secretes several adipokines, such as Leptin, Adiponectin, TNFα, IL1β, and IL6, which promote chronic inflammatory responses and are shown to be highly correlated with bone cancer metastasis and markers for the progression of bone diseases such as osteoporosis." (PMID 39056808, 2024). "In postmenopausal women, estrogen deficiency can cause an increase in various cytokines, such as IL-1, IL-6, and TNFα, which induce an increase in RANKL, thereby stimulating osteoclastogenesis and, therefore, playing a fundamental role in the pathophysiology of osteoporosis." (PMID 36829932, 2023). "Therefore, it can be seen that TNF-α and IL-6 may affect osteoclast function and lead to osteoporosis through the OPG/RANK/RANKL axis." (PMID 38041076, 2023). "The conclusions are consistent with findings in menopause-related osteoporosis, where excessive trans- (not cis-) IL-6 signaling causes loss of trabecular bone, mirroring the gain of trabecular bone through cis-IL6-induced cholinergic signals." (PMID 35276096, 2022). "Pathophysiological hypotheses reported that proinflammatory cytokines like IL-6 along with matrix GLA protein and growth factors are associated with bone turnover and in turn have a role in bone loss or osteoporosis in patients with ischemic cardiovascular diseases." (PMID 34938374, 2021). "Thus, the effects of NHA and HAD on RANKL-induced osteoclastogenesis and on OVX-induced osteoporosis in mice could be explained by the inhibition of IL-6/STAT3." (PMID 34833909, 2021). "Previous clinical studies found that IL-6 and other inflammatory cytokines accelerate bone destruction and osteoporosis via upregulation of the expression and the signal transduction of RANKL and on osteoblasts, increasing vertebral fractures and the severity of bone loss or osteoporosis." (PMID 34938374, 2021). "Therefore, it can be speculated that bone loss caused by a low-temperature environment after 14 days is closely related to IL-6 and controlling the expression level of IL-6 may represent a potential target for osteoporosis treatment." (PMID 35126308, 2021). "However, due to the limited number of studies on IL-6 572C/G and osteoporosis risk, Begg’s funnel plot was not performed to explored publication bias." (PMID 32466786, 2020).
osteoporosis (continued). "An increase in the risk of MDD with increasing levels of IL-6 mRNA has been reported in previous studies undertaken in the developed world both among persons living with HIV (PLWHA) and in other medical conditions such as cancer, cardiovascular disease, osteoporosis and among the elderly." (PMID 29298663, 2018). "The expression of inflammatory factors, such as interleukin-1 beta (IL-1β), IL-6, IL-17, and TNF-α, is markedly increased as osteoporosis progresses." (PMID 40873591, 2025). "In the prospective clinical cohort, we observed a clear dose-response relationship, with IL-1β, IL-6, and TNF-α levels showing significant graded increases across the control, osteopenia, and osteoporosis groups." (PMID 41451124, 2025). "Curculigoside is likely to treat osteoporosis through targets such as MMP3, MMP9, IL-6, and caspase-3, acting on signaling pathways including Rap1 and TNF." (PMID 40917365, 2025). "During estrogen deficiency, the activation of IL-17 significantly contributes to osteoporosis by increasing the secretion of RANKL, TNF-α, and IL-1 and IL-6, promoting bone resorption." (PMID 40496246, 2025). "In treated osteoporosis patients, there was a significant decrease in plasma levels of IFN-γ, IL-17, IL-23, and IL-6." (PMID 38817601, 2024). "In osteoporosis patients, there is a notable elevation in serum baseline levels of tryptase, IFN-γ, IL-1β, and IL-6." (PMID 38817601, 2024). "Studies have suggested that pro-inflammatory markers such as IL-6, IL-1, and TNF-alpha act as modulators of osteoblasts and osteoclasts, leading to up-regulation of osteoclast activation and osteoporosis." (PMID 38721534, 2024). "The expression of numerous inflammatory factors (IL-1β, IL-6, IL-17, and TNF-α) markedly increased during the progression of osteoporosis." (PMID 38895114, 2024). "Elderly male patients with osteoporosis had higher expression of RANKL/OPG, TNF-α, IL-6, and lower expression of IFN-γ and IL-10." (PMID 38817601, 2024). "Age, years since menopause, and circulating IL-6, PTH, and IGFBP-3 were significantly higher in the osteoporosis group compared to the normal group." (PMID 37035758, 2023). "In the study of postmenopausal women with H-type hypertension and osteoporosis, CTX-I was directly related to both TNF-α and IL-6." (PMID 36830779, 2023). "Compared to the normal women, age, years duration of menopause, and circulating IL-6, PTH, and IGFBP-3 were significantly higher in the osteoporosis women." (PMID 37035758, 2023). "In patients with end-stage renal disease, proinflammatory cytokines (IL-6 and TNF-α) are also attributed to osteoporosis." (PMID 37870853, 2023). "The mean values of the serums of IL-1β, IL-6 and TNF-α in the osteoporosis group were significantly higher than those in the non-osteoporosis group (P < 0.05)." (PMID 37038178, 2023). "The majority of proinflammatory cytokines such as IL-6, TNF-α, IL-1, and IFN-γ play a pivotal role in the treatment of osteoporosis through exercise." (PMID 36568096, 2022). "Among them, IL6, CXCR4, IGF1, and PLOD2 were finally included in this study for follow-up analysis, because the relationships between these genes and weightlessness osteoporosis remained unclear, which was worth further analyzing." (PMID 35479581, 2022). "Inflammation mediated osteoporosis presented apparently down-regulated in OPN and OCN levels, higher serum IL-1β, TNF-α, IL-6 levels in ovariectomized rats." (PMID 36387862, 2022). "Osteoporosis is mediated by a variety of inflammatory mediators, including TNF-α, RANKL, interleukin 1 beta, IL-6, and interferon gamma." (PMID 35187034, 2022). "For example, IL-1, IL-6, and TNF-α belong to the critical pro-inflammatory cytokines involved in osteoporosis and gout." (PMID 36615792, 2022). "Subsequent cellular studies confirmed that lncMIAT promoted the secretion of IL-6, TNF-α and IL-1β, which were important inflammatory cytokines for the disease progression of osteoporosis." (PMID 35381577, 2022).